RHBDF2 (rhomboid 5 homolog 2)
Description:
Regulates ADAM17 protease, a sheddase of the epidermal growth factor (EGF) receptor ligands and TNF, thereby plays a role in sleep, cell survival, proliferation, migration and inflammation. Does not exhibit any protease activity on its own.
Synonyms: iRhom2; RHBDL5; RHBDL6; FLJ22341; TOCG; TOC
Tractability: Antibody: UniProt places it where antibodies can reach, with high confidence; its Gene Ontology location is reachable by antibodies, with high confidence; UniProt predicts a signal peptide or a membrane-spanning region. PROTAC: ubiquitination databases record sites on it; its protein half-life has been measured.
Gene: Protein-coding gene on chromosome 17 (76,470,891 to 76,501,790, reverse strand). Ensembl gene ENSG00000129667.
Subcellular location: Endoplasmic reticulum membrane; Cell membrane
Pathways (Reactome):
Disease: CD163 mediating an anti-inflammatory response
Gene Ontology:
Molecular function: protein binding; cargo receptor activity; serine-type endopeptidase activity
Biological process: negative regulation of inflammatory response to antigenic stimulus; negative regulation of protein secretion; regulation of epidermal growth factor receptor signaling pathway; regulation of protein secretion; gene expression; hair cell differentiation; hair follicle cell proliferation; hair follicle morphogenesis; positive regulation of Notch signaling pathway; protein maturation; vesicle-mediated transport
Cellular component: plasma membrane; endoplasmic reticulum membrane; Golgi lumen; cytoplasm; endomembrane system; membrane
Genetic constraint (gnomAD): Loss-of-function variants: 38 observed, 91.37 expected, observed/expected ratio (o/e) 0.42, 90% interval 0.32 to 0.55. The upper end of that interval is the gene's LOEUF score, 0.55, which puts it in group 2 of 6, group 1 being the genes least tolerant of losing a copy. Missense variants: 863 observed, 1,118.9 expected, observed/expected ratio (o/e) 0.77, 90% interval 0.73 to 0.82. Synonymous variants: 442 observed, 454.61 expected, observed/expected ratio (o/e) 0.97, 90% interval 0.9 to 1.05.
Gene-disease validity (ClinGen):
ClinGen rates the evidence that RHBDF2 causes each of these diseases.
palmoplantar keratoderma-esophageal carcinoma syndrome (autosomal dominant): Definitive. An inherited condition characterized by palmoplantar keratoderma and esophageal cancer.
Homologues: Orthologues: macaque RHBDF2 (99% identical), dog RHBDF2 (95% identical), pig RHBDF2 (93% identical), guinea pig RHBDF2 (92% identical), mouse Rhbdf2 (92% identical), rabbit RHBDF2 (92% identical), chimpanzee RHBDF2 (91% identical), rat Rhbdf2 (90% identical), tropical clawed frog rhbdf2 (74% identical), Caenorhabditis elegans rom-4 (33% identical), Caenorhabditis elegans rom-3 (30% identical), Drosophila melanogaster rho-5 (21% identical). Paralogues in human: RHBDF1 (59% identical), RHBDL3 (10% identical), RHBDL1 (10% identical), PARL (9% identical), RHBDL2 (9% identical).
Diseases named in the same sentence as RHBDF2 in open-access papers:
RHBDF2 is named in the same sentence as 87 diseases in open-access papers, as found by Europe PMC text mining. Sharing a sentence is not in itself a finding about the gene and the disease. The quoted sentences say what the papers report.
tylosis (19 papers, 2014 to 2024). "A previous study showed that RHBDF2 mutations are closely associated with tylosis, a familial EC syndrome." (PMID 36591498, 2022). "In humans, dominant mutations in RHBDF2 cause tylosis with esophageal cancer (TOC) syndrome through a hyperactive EGFR signaling pathway." (PMID 34477920, 2021). "Gain-of-function (GOF) mutations in the human rhomboid 5 homolog 2 (RHBDF2) gene constitutively activate epidermal growth factor receptor (EGFR) signaling to cause tylosis with esophageal cancer syndrome (TOC; OMIM: 148500)." (PMID 30022999, 2018). "In humans, autosomal dominant mutations in RHBDF2 cause tylosis, a form of focal nonepidermolytic palmoplantar keratoderma (PPK) that manifests on the skin of the palms and soles." (PMID 28655741, 2017). "We generated a mouse model of human tylosis and show that GOF mutations in RHBDF2 cause tylosis by enhancing the amount of amphiregulin (AREG) secretion." (PMID 28655741, 2017). "Tylosis with esophageal cancer (TOC) is a rare, autosomal dominant syndrome associated with late-onset focal nonepidermolytic palmoplantar keratoderma, germline mutations in RHBDF2 (encoding iRhom2), and a high lifetime risk of ESCC, estimated to be 90% by 70 years." (PMID 39131151, 2024). "Moreover, germline mutations in the RHBDF2 gene (17q25) which cause tylosis (focal non-epidermolytic palmoplantar keratoderma) have been reported to be markers of genetic familial susceptibility for the early onset of ESSC." (PMID 32751137, 2020). "In humans, gain-of-function (GOF) mutations in RHBDF2 cause the skin disease tylosis." (PMID 28655741, 2017). "It is the combination of family history of both tylosis and oesophageal cancer, late onset skin lesions (i.e. substantially after birth but before puberty) and, more recently, the demonstration of mutation in RHBDF2 that enable differential diagnosis." (PMID 26419362, 2015). "Tylosis with esophageal cancer (TOC) is a rare syndrome associated with a high lifetime risk of ESCC and germline mutations in RHBDF2, encoding iRhom2." (PMID 39131151, 2024). "Mutations in RHBDF2 accelerate tumorigenesis by activating epidermal growth factor receptor (EGFR) signaling and are associated with tylosis esophageal cancer." (PMID 33796525, 2021). "Together, these previous observations and results from our present study provide valuable background information for future studies aimed at testing keratinocyte-specific effects of RHBDF2 in tylosis in skin tissue." (PMID 29116018, 2017). "The well-documented association between EC and RHBDF2 gene at 17q25 in tylosis (a rare genetic disease characterized by focal nonepidermolytic palmoplantar keratoderma) adds to the evidence." (PMID 38962101, 2024). "Here, we generated mice carrying a human GOF mutation p.P189L (p.P159L in mice) in RHBDF2 to examine whether GOF mutations in human RHBDF2 lead to enhanced AREG secretion and tylosis." (PMID 28655741, 2017). "Tylosis, a genetic disease characterized by hyperproliferation of skin in the palms and soles, loss of hair, and oral leukoplakia, is caused by gain-of-function (GOF) mutations (p.I186T, p.P189L, and p.D188N) in the human rhomboid family protein RHBDF2." (PMID 29116018, 2017). "The curly bare mouse model of tylosis, carrying a GOF mutation in the Rhbdf2 gene (Rhbdf2cub), presents with epidermal hyperplasia and shows accelerated cutaneous wound-healing phenotype through enhanced secretion of the epidermal growth factor receptor family ligand amphiregulin." (PMID 29116018, 2017). "Thus, it is possible that GOF mutations in RHBDF2, such as Rhbdf2cub/cub and Rhbdf2P159L/P159L, influence TNFA secretion, contributing to tylosis." (PMID 29116018, 2017). "Together, these results, along with the recent findings that mutations in Rhbdf2 in mice result in enhanced EGFR pathway activation, suggest a possible mechanism for the association between RHBDF2 mutations and tylosis." (PMID 28655741, 2017).
tylosis (continued). "Collectively, our data suggest that RHBDF2 plays a critical role in regulating EGFR signaling and its downstream events, including development of tylosis, by facilitating enhanced secretion of AREG." (PMID 28655741, 2017). "The role of RHBDF2 in enhancing amphiregulin (AREG) secretion, and consequently activating the epidermal growth factor receptor (EGFR) pathway, has significance for the skin disease tylosis." (PMID 28655741, 2017).
oesophageal cancer (10 papers, 2014 to 2024). "The development of esophageal carcinoma due to palmoplantar keratosis is associated with a genetic mutation (RHBDF2 on 17q25.1) with the autosomal dominant pattern." (PMID 39211646, 2024). "Here the authors show that K16 interacts with the inactive protease Rhbdf2, associated with Tylosis with oesophageal cancer, and that this interaction drives increased keratinocyte proliferation." (PMID 28128203, 2017).
esophageal cancer (9 papers, 2016 to 2026). A primary or metastatic malignant neoplasm involving the esophagus. "In vivo, Rhbdf2 has been implicated in esophageal cancer, wound healing, bone marrow repopulation by monocytic cells, and inflammatory arthritis." (PMID 32094386, 2020).
Alzheimer disease (7 papers, 2019 to 2025). A progressive, neurodegenerative disease characterized by loss of function and death of nerve cells in several areas of the brain leading to loss of cognitive function such as memory and language. "This study demonstrates that the Alzheimer’s disease risk factor iRhom2/RHBDF2 is a modifier of microglial TREM2 proteolysis and establishes ADAM17 as a physiological TREM2 protease in microglia." (PMID 40081988, 2025). "Rhomboid 5 Homolog 2 (RHBDF2) was found to be differentially methylated in the central nervous system (CNS) in Alzheimer’s disease." (PMID 32849827, 2020). "Previous study showed that RHBDF2 RNA methylated levels was involved in Alzheimer's disease." (PMID 40898058, 2025). "Similarly, in our study utilizing KEGG gene sets, we found that oxidative phosphorylation, citrate cycle (TCA cycle), Alzheimer’s disease, and selenoamino acid metabolism were inhibited in the high expression groups of RHBDF2 and TNFRSF10B." (PMID 38915415, 2024).
gastric cancer (5 papers, 2020 to 2024). A primary or metastatic malignant neoplasm involving the stomach. "The authors demonstrated that RHBDF2 regulates TGF-β signaling, and CAFs with high RHBDF2 expression induce lymphatic invasion of gastric cancer cells in a mouse model." (PMID 38562556, 2024). "Rhomboid 5 homolog 2 (RHBDF2) induces gastric cancer cell invasiveness by regulating Transforming Growth Factor Beta 1 (TGFB1) signaling, a finding that corresponds with our results." (PMID 33796525, 2021). "A recent report demonstrated that inflammatory cytokines IL-1α, IL-1β or TNFα secreted by diffuse-type gastric cancer cells induced upregulation of rhomboid 5 homolog 2 (RHBDF2), also termed iRhom2 in cancer-associated fibroblasts (CAFs)." (PMID 32698506, 2020).
atherosclerosis (4 papers, 2019 to 2026). A disease characterized by the build-up of fatty material and calcium deposition in the arterial wall resulting in partial or complete occlusion of the arterial lumen. "Rhomboid 5 homolog 2 (Rhbdf2), also known as iRhom2, is an inactive member of the rhomboid intramembrane proteinase family that has been determined to be a pivotal pathogenic regulator of inflammation-related diseases, e.g., obesity, arthritis, nephritis, atherosclerosis, and fibrosis." (PMID 35217669, 2022).
Hepatic steatosis (4 papers, 2022 to 2025). Steatosis is a term used to denote lipid accumulation within hepatocytes. "Our previous studies have also indicated that upregulated Rhbdf2 triggered by HFD significantly drives progression of NAFLD/NASH pathological phenotype in vivo, revealing a potential treatment prospect of Rhbdf2 in liver steatosis-associated metabolic disorders." (PMID 35217669, 2022). "The observed effects of Trim31 on Rhbdf2 signaling-associated hepatic steatosis, inflammation, and insulin resistance prompted us to examine whether Trim31 directly interacts with Rhbdf2 during the development of NAFLD." (PMID 35217669, 2022). "In our present work, we found that Trim31 has the ability to suppress liver steatosis and improve insulin signaling and hepatic inflammation by promoting Rhbdf2 degradation via K48-linked ubiquitination, further restraining Rhbdf2-MAP3K7 activity and downstream events." (PMID 35217669, 2022). "Once the interaction between Rhbdf2 and Trim31 was blocked, the protective function of Trim31 on HFD-induced liver steatosis was strongly inhibited." (PMID 35217669, 2022).
liver fibrosis (4 papers, 2020 to 2025). "HSCs lacking Rhbdf2 that is required for ADAM17 maturation, displayed reduced TNFR1 and 2 shedding and as a consequence of enhanced TNF signalling, Rhbdf2-/- mice displayed enhanced bile duct obstruction-induced liver fibrosis." (PMID 32698506, 2020).
Insulin resistance (3 papers, 2022 to 2025). Increased resistance towards insulin, that is, diminished effectiveness of insulin in reducing blood glucose levels. "Furthermore, the hepatic Trim31 expression in mice is responsive to dietary interventions that significantly moderated insulin resistance, hepatic steatosis, and inflammation phenotype via mechanically, regulating Rhbdf2 proteasome degradation." (PMID 35217669, 2022). "Therefore, Trim31-Rhbdf2 binding and the subsequent Rhbdf2 ubiquitination are required for and conduce to the mitigation of liver steatosis, insulin resistance, and liver inflammation triggered by hepatocyte Rhbdf2-MAP3K7 signaling." (PMID 35217669, 2022).
steatosis (3 papers, 2022 to 2023). Increased lipid within the cytoplasm of cells. "The gene for rhomboid 5 homolog 2 (IRHom2), which encodes the rhombus protease iRhom2, activates the MAP3K7‐dependent pathway and promotes hepatic steatosis." (PMID 36943228, 2023). "In patients with NAFLD or NASH, we found that Trim31 levels were drastically reduced, but hepatic Rhbdf2 levels were increased, compared to the levels in non-steatosis samples." (PMID 35217669, 2022). "Meanwhile, higher expression levels of Rhbdf2 were further observed in the livers of NASH patients than in the livers of patients with only simple steatosis." (PMID 35217669, 2022).
breast carcinoma (2 papers, 2022 to 2025). "Consistent with this, in silico analysis of publicly available gene expression data-sets on breast cancer showed heterogeneous expression behaviour of RHBDF2 according to the intrinsic molecular subtypes and histopathological grading and staging." (PMID 36452073, 2022).
cervical carcinoma (2 papers, 2020 to 2023). A carcinoma arising from either the exocervical squamous epithelium or the endocervical glandular epithelium. "High RHBDF2 expression can induce enhanced EGFR, WNT and transforming growth factor (TGF)‐β signaling, and was dramatically linked to poor prognosis of cervical cancer." (PMID 36943228, 2023).
esophageal squamous cell carcinoma (2 papers, 2014 to 2020). Esophageal squamous cell carcinoma (ESCC) is a type of esophageal carcinoma (EC) that can affect any part of the esophagus, but is usually located in the upper or middle third. "One study reported that a missense mutation of RHBDF2, a gene of rhomboid family encoding iRom2, is critical in the development of esophageal squamous cell carcinoma." (PMID 24977233, 2014).
amyotrophic lateral sclerosis (1 paper, 2020). Amyotrophic lateral sclerosis (ALS) is a neurodegenerative disease characterized by progressive muscular paralysis reflecting degeneration of motor neurons in the primary motor cortex, corticospinal tracts, brainstem and spinal cord. "In addition, a differentially methylated region located in the promoter–enhancer region of the RHBDF2 gene was identified in amyotrophic lateral sclerosis (ALS) patients in ccfDNA in the plasma." (PMID 32849827, 2020).
brain hemorrhage (1 paper, 2021). "Why does RHBDF2 not rescue multiorgan pathology, including brain hemorrhage and cardiac fibrosis, in Rhbdf1-null mice?" (PMID 34477920, 2021).
cerebral infarction (1 paper, 2025). An ischemic condition of the brain, producing a persistent focal neurological deficit in the area of distribution of the cerebral arteries. "Accordingly, M2 microglia was enriched in the cerebral infarction tissues of MCAO/R mice, and the percentage of M2 microglia was further increased with RHBDF2 knockdown." (PMID 40898058, 2025).
Cerebral ischemia (1 paper, 2025). Restriction of arterial blood supply to the brain associated with insufficient oxygenation to support the metabolic requirements of the tissue. "YTHDF1 promoted RHBDF2 translation in an m6A-dependent manner in microglia after cerebral ischemia and reperfusion injury." (PMID 40898058, 2025).
Hepatitis (1 paper, 2023). Inflammation of the liver. "Notably, we found that there is a noticeable link between RHBDF2 and worse RFS and PFS in HCC patients with a hepatitis history, and poor OS and DSS in HCC patients without a hepatitis history." (PMID 36943228, 2023).
ischemic stroke (1 paper, 2025). A stroke disorder caused by obstruction of blood flow to the brain, due to thrombotic (local blood clot formation) or embolic (due to a blood clot or other material traveling from another site) event. "In particular, the expression of RHBDF2 was significantly upregulated in microglia after ischemic stroke." (PMID 40898058, 2025). "This suggests RHBDF2 as a potential therapeutic target in ischemic stroke." (PMID 40898058, 2025). "Therefore, our study suggests that RHBDF2 might be a promising therapeutic target for the treatment of ischemic stroke." (PMID 40898058, 2025).
lymph node metastasis (1 paper, 2023).
myocarditis (1 paper, 2026). Myocarditis is a condition that is characterized by inflammation of the heart muscle (myocardium). "This case describes a case of acute abemaciclib-induced myocarditis and explores a potential genetic predisposition involving an RHBDF2 germline variant affecting growth factor signalling pathways." (PMID 41535991, 2026).
Palmoplantar keratoderma (1 paper, 2018). Abnormal thickening of the skin of the palms of the hands and the soles of the feet. "Inherited gain-of-function mutations in RHBDF2 (encoding iRHOM2) are associated with a hyperproliferative palmoplantar keratoderma and squamous oesophageal cancer syndrome (termed TOC)." (PMID 29523849, 2018).
renal carcinoma (1 paper, 2021). A carcinoma arising from the epithelium of the renal parenchyma or the renal pelvis. "Silencing the RHBDF2 gene in renal cancer cells leads to down-regulation of the immunosuppressive checkpoint protein PD-L1, even though there is an increase of lymphocyte infiltration into the tumors with high levels of RHBDF2." (PMID 34736454, 2021). "We then prepared shRNA lentivirus to artificially knockdown RHBDF2 in renal cancer cell-lines (786-O and 769-P)." (PMID 34736454, 2021).
renal clear cell cancer (1 paper, 2021). "In order to further investigate the biological characteristics of renal clear cell carcinoma that are associated with various levels of RHBDF2 expression, we carried out WGCNA." (PMID 34736454, 2021). "In summary, we found that RHBDF2 is positively correlated with the severity of the malignancy of renal clear cell carcinoma." (PMID 34736454, 2021). "RHBDF2 gene functions are correlated to facilitated renal clear cell carcinoma progression and may serve as a critical prognostic biomarker for the disease." (PMID 34736454, 2021). "To verify the results from bioinformatics analysis that the genes and pathways related to RHBDF2 functions may contribute to cancer cell migration and signal transduction, we silenced the RHBDF2 gene by using shRNA in renal clear cell carcinoma cell line 786-O and 769-P." (PMID 34736454, 2021).